LEP (leptin)
Diseases named in the same sentence as LEP in open-access papers (continued):
Sharing a sentence is not in itself a finding about the gene and the disease.
Obesity (continued). "The results of the present study, using a swine model of obesity due to leptin resistance (Iberian pig) indicate that the fetuses from leptin-resistant genotypes have a decreased antioxidant capacity and, in consequence, a higher systemic oxidative stress than lean crossbred fetuses." (PMID 30288483, 2018). "Importantly, mice with whole body or neuron-specific deletion of PTP1B are hypersensitive to leptin and resistant to diet-induced obesity." (PMID 30383868, 2018). "The two leptin gene variants associated with CRC risk in women were not concomitantly associated with obesity (p = 1.00)." (PMID 30379922, 2018). "In a recent study, AA showed an anti-obesity action in high-fat food fed rat model of obesity as evidenced by the improved antioxidant activities, regulation of lipid metabolism, and insulin and leptin sensitivity in addition to reduction in body weight gain." (PMID 30233358, 2018). "Disentangling causes from effects leptin resistance is not necessarily the result of obesity, and some kinds of dietary sugars (e.g., fructose) have been shown to induce leptin insensitivity regardless of body weight gain." (PMID 29740277, 2018). "Adipose tissue expression and plasma leptin levels are elevated in obesity, leading to the concept of functional leptin resistance, but its mechanism remains unknown." (PMID 29795184, 2018). "Both the LEP and LEPR genes have been studied for polymorphisms that could possibly be related to the pathophysiology of obesity and its complications among specific ethnic groups." (PMID 30583468, 2018). "In obesity, excess adipose tissue leads to hyperleptinemia and leptin resistance as well as increased production of pro-inflammatory cytokines resulting in decreases in whole body insulin sensitivity and disruption in appetite control and regulation of food intake." (PMID 30258366, 2018). "Furthermore, reduction of mast cells in leptin-deficient ob/ob mice exacerbated obesity and diabetes, indicating an important role of mast cells in obesity-related inflammation through its reactivity to leptin levels." (PMID 29910742, 2018). "Mechanistically, the anti-obesity effect of these cytokines was mediated by inhibition of IKKβ activation and endoplasmatic reticulum stress leading to restoration of central insulin and leptin sensitivity." (PMID 30158466, 2018). "The children with obesity had elevated serum leptin and proinsulin (p < 0.001) concentrations." (PMID 30275363, 2018). "For obesity-related phenotype, first, we measured the leptin content in brain and muscle by ELISA." (PMID 30551684, 2018). "This selective LR could be correlated with a previous theory that HFD-induced obesity required the blockade of leptin action for surplus calorie storage." (PMID 30405527, 2018). "It is possible that elevated leptin and/or leptin resistance observed in obesity may be contributing to OSA." (PMID 30127766, 2018). "Little is known regarding the mechanism that leads to leptin resistance in obesity." (PMID 30131766, 2018). "In addition to these microbiome changes, we observed the development of several features of the metabolic syndrome, including obesity, glucose intolerance, insulin resistance, fatty liver, adipocyte hypertrophy and increased circulating leptin." (PMID 29973701, 2018). "Leptin was typically increased, and adiponectin levels were decreased, with obesity." (PMID 30208589, 2018). "This monogenetic obesity is corrected by treatment with recombinant leptin." (PMID 29748097, 2018). "It is likely that the majority of obesity does not stem from single factor causes (such as mutations in the leptin system), but rather from the upper extreme of the normal population distribution of BMI46." (PMID 29679049, 2018). "Thus, these adaptive changes in synaptic strength appear to be a hallmark feature of negative energy balance (in the case of fasting) as well dysregulated energy balance (in the case of obesity and insulin/leptin resistance)." (PMID 29973869, 2018).
Obesity (continued). "However, the opposite effect was reported to occur when IL4 was administered intracerebroventricularly (icv) to rats during HFD feeding, that is, exacerbation of obesity, further hypothalamic inflammation as well as leptin and insulin resistance." (PMID 30158466, 2018). "Leptin and neuropeptide Y can be potential targets for future anti-obesity medications." (PMID 30254821, 2018). "However, further studies are required to clarify the molecular mechanisms by which RSV regulates leptin signaling in obesity." (PMID 30441779, 2018). "Leptin resistance is likely involved in the pathogenesis of obesity and thus T2D." (PMID 30428550, 2018). "We observed that striped hamsters that were refed with high-fat diet had considerable up-regulation of leptin expression, but developed obesity compared to those fed with low-fat diet, suggesting that some components of leptin signaling may impaired." (PMID 29343842, 2018). "Impairment of leptin production or signaling leads to obesity and reduced metabolic rate." (PMID 30186233, 2018). "Therefore, Y123F mice are more suitable to be a new animal model to investigate the role of leptin and lepR in reproduction, especially in obesity-related infertility." (PMID 29728128, 2018). "In addition, the absolute role of leptin resistance in the gain of body weight or the maintenance of obesity has been queried." (PMID 29777232, 2018). "The obesity usually manifests by 2-3 years of age, unlike that found in patients with LEP gene mutation which manifests in early infancy." (PMID 29217499, 2018). "Possible mechanisms include comorbid hypothyroidism, decreased resting metabolic rate, preference for high carbohydrate foods, certain behavioral tendencies that increase with age and high leptin levels; increased leptin levels from leptin resistance correlate with obesity." (PMID 29587359, 2018). "Leptin is an adipokine secreted hormone in proportion to the amount of adipose tissue and its concentrations increase with caloric intake and decrease during the fasting period, being elevated in obesity." (PMID 29322840, 2018). "The tobacco smoking is associated with the toxicity nicotine and carbon monoxide whose depress the development of the immune system in fetus and disturb adipocytes tissue hormone leptin activity which can result in metabolic disorders and obesity in later life." (PMID 29510565, 2018). "The alterations of leptin and hypothalamic pituitary adrenal (HPA) axis dysfunction, adipocyte function, and fatty acid levels and oxidative stress have been suggested to play a vitally important role in obesity-associated inflammation." (PMID 29643982, 2018). "Whether this link is predominantly permissive for diagnostic value, further in-depth exploration of the interplay of “Leptin-Obesity-Kisspeptin-Fertility” at molecular levels is expected to shed light in future." (PMID 29805405, 2018). "Indeed, resistance to anorexigenic signaling pathways are well-characterized in obesity (e.g., leptin and insulin), including neuropeptides such as CARTPT." (PMID 29746501, 2018). "It is thought that adiponectin opposes the effects of leptin in obesity." (PMID 30510663, 2018). "Sex differences in the regulation and action of leptin, different states of immune activation, and the effects of sex steroids may explain the differences in BMI and obesity between genders in patients with HIV." (PMID 30505292, 2018). "Low levels of circulating leptin and compromised leptin signalling may account for the extreme obesity seen in this case." (PMID 29217499, 2018). "In contrast to adiponectin, leptin increases in circulation with obesity, and has central effects on bone metabolism and direct effects on bone cells which may also influence the skeleton." (PMID 29364924, 2018). "Interestingly, leptin has a crucial role in mediating phagocytosis, T cell number, function, and metabolism in both obesity and malnutrition." (PMID 30534129, 2018).
Obesity (continued). "Leptin, an adipokine upregulated during obesity, has been widely studied in carcinogenesis because of its many signalling pathways involved in critical steps of pathogenesis such as cell proliferation, inflammatory response and modulation of the tumour environment." (PMID 30563501, 2018). "Since obesity and obesity-related infertility/subfertility are growing problems in human beings, our finding that direct effects of leptin and lepR on ovary were involved in infertility of Y123F mice, suggested a new viewpoint on the relationship between obesity and reproduction." (PMID 29728128, 2018). "Leptin methylation pattern can be influenced by diet-induced obesity for 11 weeks." (PMID 30424542, 2018). "Nevertheless, in non-pregnant Brazilian women, associations with obesity risk and increased leptin levels for 2548GG genotype and 2548G allele were reported." (PMID 30618791, 2018). "The novel finding of direct actions of leptin on the ovary may account for some adverse effects of obesity on ovarian function." (PMID 29728128, 2018). "However, leptin resistance results in failure to control weight, with high level of leptin expression in the plasma, and leads to obesity." (PMID 30551684, 2018). "Although obesity increases serum leptin concentration, there is no corresponding loss of appetite, which suggests resistance of individuals to the actions of this hormone." (PMID 29479505, 2018). "However, studies also indicated that, in obesity with LR, leptin still retained actions that resulted in the development of hypertension, which is known as selective LR." (PMID 30405527, 2018). "Interestingly, both obesity and malnutrition are related to aberrant leptin levels, obesity due to chronically elevated leptin levels, whereas malnutrition results in significantly diminished leptin levels." (PMID 30534129, 2018). "Moreover, leptin is involved in both innate and adaptive immunity, suggesting a potential role of leptin in obesity-mediated inflammation." (PMID 30333759, 2018). "Current hypotheses suggest that leptin, which is also known as an obesity hormone or fat hormone, plays a vital role in BC development, and high serum leptin levels are associated with an increased risk for BC." (PMID 29370782, 2018). "Therefore, it is plausible that obesity exerts its effect on leptin and that leptin subsequently participates in increasing blood pressure by slowly increasing sympathetic nervous system activity." (PMID 29636702, 2018). "In addition, data from animal studies show that diet-induced inflammatory response in the hypothalamus can lead to central leptin resistance and obesity." (PMID 29675134, 2018). "In addition, obesity as well as elevated levels of adipokines, such as leptin and adiponectin, are commonly found in psoriasis and type 2 DM35–37." (PMID 29904118, 2018). "One important factor potentially linking obesity to the timing of puberty is leptin." (PMID 29321542, 2018). "Increased levels of H3K9me2 were found in the promoter of adiponectin, whereas increased levels of H4K20me1 (a permissive histone modification) was found in the leptin promoter, suggesting that histone modifications play a significant role in conferring obesity and metabolic syndrome phenotypes." (PMID 29922517, 2018). "Whereas knockout of Il-1r1 gene causes leptin resistance and obesity, Ptpn1 knockout results in negative energy balance, protection from weight gain and improved insulin sensitivity." (PMID 29371411, 2018). "To further evaluate the relevance of leptin-reactive IgG to the patient phenotype, we studied whether their plasma levels and affinity kinetics correlated with clinical traits of obesity and diabetes." (PMID 29795184, 2018). "Conversely, in obesity, leptin participates in the pro-inflammatory processes." (PMID 30510663, 2018). "The observation that hyperleptinemia per se, and thus chronically higher LEPR signaling, is upstream of leptin resistance in obesity could imply a pharmacological ceiling effect." (PMID 29748097, 2018).
Obesity (continued). "Thus, in the present study we purified, characterised, and partially sequenced the trypsin inhibitor of the tamarind seed, reevaluating its effect upon plasmatic CCK and leptin in an experimental model of obesity." (PMID 29322840, 2018). "Also, leptin and leptin receptor gene defects result in human obesity and delayed puberty, oligo-anovulation, or subfertility in most human populations." (PMID 29728128, 2018). "The mutations identified to date in LEP and LEPR are ethnic-specific, and the prevalence of monogenic obesity caused by mutations within these two genes is as high as > 20% in Pakistani study populations with obesity." (PMID 30442103, 2018). "Indeed, PDAC cells treated with 5FU showed a significantly higher proliferation rate and higher levels of EMT when contemporarily exposed to leptin, thus individuating a potential role of obesity in determining chemoresistance via EMT." (PMID 30366466, 2018). "Leptin signaling is involved in obesity and its cardiovascular complications." (PMID 30131073, 2018). "Maternal overweight/obesity and GDM are associated with adverse short- and long-term outcomes in the offspring, the latter identified to be related especially to increased birth weight, insulin and leptin." (PMID 29925339, 2018). "At present, the epigenetic modifications that control the leptin promoter in obesity remain unclear, but our findings are probably a reflection of a decrease in appetite and therefore a reduction in the need for high amounts of leptin." (PMID 29959379, 2018). "The disparity in leptin serum level and receptor expression may be more representative of what occurs in an obese human and may be contributing to the comorbidity of obesity and MDD." (PMID 30405455, 2018). "In the same line of findings, it has been exposed that obesity and overnutrition-induced inflammation could promote hypothalamic ER stress, leading to insulin and leptin resistance and, ultimately to weight gain." (PMID 30018241, 2018). "Thus, in this study, we analyzed plasma samples from healthy subjects and patients with obesity and/or type 2 diabetes (T2D) to characterize circulating IgG autoAbs reactive with leptin." (PMID 29795184, 2018). "Accordingly, leptin-deficient or LepR-deficient mice developed extreme obese phenotype without increased incidence of knee OA, suggesting that leptin signaling is essential to the development and progression of obesity-associated OA." (PMID 29910742, 2018). "As an appetite-related hormone, leptin may play an important role in weight regain after obesity therapy." (PMID 29849871, 2018). "Furthermore, plasma ghrelin levels have been reported to be reduced in animal models of obesity and in obese subjects, being inversely correlated with adiposity, fasting insulin, and leptin." (PMID 29618984, 2018). "Similarly, in individuals with both obesity and type 2 diabetes, leptin was positively correlated with lipid peroxidation and protein oxidation." (PMID 30205427, 2018). "In contrast, leptin had a larger fluctuation and much lower scope, ranging from 5 to 20 ng/ml in non-overweight people, but reaching to 50 ng/ml or greater in overweight and obesity individuals." (PMID 30013512, 2018). "Thus, when it was found that the ratio of leptin in the CSF to leptin in circulation is lower with obesity it was proposed that this reflects a saturation/impairment in leptin transport across the BBB that drives leptin resistance." (PMID 29748097, 2018). "The proposed mechanism is that sleep may influence cancer risk via alterations in levels of appetite-regulating hormones, such as leptin and ghrelin, leading to increased appetite and subsequent obesity." (PMID 30463535, 2018). "When leptin was first discovered, it was lauded as a potential treatment for obesity." (PMID 30373146, 2018). "Therefore, it is anticipated that an orally absorbable PTP1B inhibitor would demonstrate anti-obesity effects by enhancing leptin sensitivity in obese subjects." (PMID 30383868, 2018).
Obesity (continued). "Changes seen in these two key hormonal systems in obese subjects allow us to predict the impact of obesity on the main metabolic organs as a consequence of modified insulin sensitivity for example, especially with the interactions between leptin and insulin and the distribution of leptin receptors." (PMID 30463389, 2018). "Interestingly, adiponectin level is inversely but leptin is directly correlated to obesity and insulin resistance." (PMID 30214412, 2018). "For instance, identifying individuals who have developed resistance to leptin, as a consequence of midlife obesity, may be pertinent as these individuals may be unresponsive to leptin-based therapies." (PMID 30386207, 2018). "Diet-induced obesity in humans' results in the increase in systemic leptin levels and its resistance is due to the desensitized LEPRs; conversely, the systemic leptin levels are reduced in malnutrition and in starvation." (PMID 29868503, 2018). "Even if it has been shown that leptin can cross the blood-testis barrier, we can hypothesize that obesity could also facilitate the passage of leptin and other adipokines through this barrier." (PMID 29971101, 2018). "Overall, the most favored hypothesis attempting to explain the hyperthyrotropinemia in subjects with obesity is the increased leptin-mediated production of pro-thyrotropin-releasing hormone (TRH)." (PMID 30250485, 2018). "Emerging hypotheses postulate that physiological components of obesity, including glycemic control, insulin action, and leptin signaling, contribute to the development of OSA." (PMID 30127766, 2018). "Importantly, the obesity-stratified logistic regression analysis adjusted for age, sex and tPa also confirmed that lower adiponectin (OR, 0.49; 95% CI, 0.38–0.64) and higher leptin (OR, 1.41; 95% Cl, 1.25–1.58) levels were predictors for PTS." (PMID 29720688, 2018). "Leptin was involved in obesity and various inflammatory processes." (PMID 29620639, 2018). "The hormones leptin and adiponectin have, in particular, been extensively studied due to their important roles in the regulation of whole-body metabolism and because circulating levels of those adipokines are altered in obesity." (PMID 29335300, 2018). "Using the ob/ob mouse, in which a mutation in the leptin gene results in excessive appetite and obesity from 6 weeks of age, it was found that obesity had a significant negative impact on the movement of cholesterol from the circulation to the faeces." (PMID 30216355, 2018). "We proposed that with heart being a high-energy-demand organ, a possible link between obesity and development of cardiovascular diseases might be related with direct effect of circulating leptin on mitochondria." (PMID 30154842, 2018). "Similarly, the first study to demonstrate defects in leptin BBB transport with obesity was conducted in one-year old outbred CD1 mice selected for leaness and heaviness." (PMID 29748097, 2018). "This supports the concept that serum leptin mediates a link between obesity and male infertility." (PMID 29855380, 2018). "Here, we review several well-known hypotheses that have been proposed to explain impaired central responsiveness to the appetite-suppressing effects of leptin in obesity." (PMID 29632515, 2018). "Moreover, diet-induced obesity, which increased leptin levels and signaling in mice hosting mammary tumors, incremented the levels of Notch3, JAG1 and survivin." (PMID 30004402, 2018). "In addition, obesity induces changes in circulating adipokines such as leptin and adiponectin which are protumorigenic." (PMID 29271901, 2017). "Likewise, the leptin-null ob/ob mice exhibit decreased energy expenditure, hyperphagia and obesity (Lindström, 2007)." (PMID 28154537, 2017). "Leptin plays a critical role in homeostatic control of food intake, and central leptin resistance is believed to be one major component of the pathogenesis of human obesity." (PMID 28645299, 2017).